CLK3 (CDC like kinase 3)
Description:
Dual specificity kinase acting on both serine/threonine and tyrosine-containing substrates. Phosphorylates serine- and arginine-rich (SR) proteins of the spliceosomal complex. May be a constituent of a network of regulatory mechanisms that enable SR proteins to control RNA splicing and can cause redistribution of SR proteins from speckles to a diffuse nucleoplasmic distribution. Phosphorylates SRSF1 and SRSF3. Regulates the alternative splicing of tissue factor (F3) pre-mRNA in endothelial cells.
Synonyms: PHCLK3; PHCLK3/152
Tractability: Small molecule: a structure with a bound ligand is known; a high-quality ligand is known; it has a high-quality binding pocket; it belongs to a druggable protein family. PROTAC: ubiquitination databases record sites on it; its protein half-life has been measured; a small molecule that binds it is known.
Target class: Protein Kinase; Enzyme; CMGC protein kinase group; Kinase; CMGC protein kinase CLK family
Chemical probes: RIGOSERTIB, T3-CLK (high quality)
Gene: Protein-coding gene on chromosome 15 (74,598,500 to 74,645,414, forward strand). Ensembl gene ENSG00000179335.
Subcellular location: Nucleus (Isoform 1); Cytoplasm; Cytoplasmic vesicle, secretory vesicle, acrosome; Nucleus speckle (Isoform 2)
Subcellular location (Human Protein Atlas): Nucleoplasm; Intermediate filaments
Gene Ontology:
Molecular function: identical protein binding; protein binding; RNA binding; protein serine/threonine kinase activity; protein tyrosine kinase activity; ATP binding; protein kinase activity; protein serine kinase activity; protein serine/threonine/tyrosine kinase activity
Biological process: protein phosphorylation; regulation of RNA splicing
Cellular component: membrane; nucleoplasm; nucleus; acrosomal vesicle; cytoplasm; nuclear speck
Genetic constraint (gnomAD): Loss-of-function variants: 22 observed, 62.18 expected, observed/expected ratio (o/e) 0.35, 90% interval 0.25 to 0.5. The upper end of that interval is the gene's LOEUF score, 0.5, which puts it in group 2 of 6, group 1 being the genes least tolerant of losing a copy. Missense variants: 498 observed, 675.01 expected, observed/expected ratio (o/e) 0.74, 90% interval 0.69 to 0.8. Synonymous variants: 249 observed, 246.61 expected, observed/expected ratio (o/e) 1.01, 90% interval 0.91 to 1.12.
Homologues: Orthologues: chimpanzee CLK3 (99% identical), dog CLK3 (99% identical), rat Clk3 (99% identical), mouse Clk3 (99% identical), pig CLK3 (99% identical), guinea pig CLK3 (97% identical), rabbit CLK3 (96% identical), macaque CLK3 (90% identical), tropical clawed frog clk3 (63% identical), zebrafish clk4a (47% identical), Drosophila melanogaster mnb (26% identical), Caenorhabditis elegans mbk-1 (25% identical), and 3 more. Paralogues in human: CLK2 (61% identical), CLK4 (50% identical), CLK1 (49% identical), DYRK1A (27% identical), DYRK1B (26% identical), DYRK4 (26% identical), DYRK3 (25% identical), DYRK2 (24% identical), HIPK2 (24% identical), HIPK1 (23% identical), HIPK3 (23% identical), HIPK4 (20% identical).
Diseases named in the same sentence as CLK3 in open-access papers:
CLK3 is named in the same sentence as 18 diseases in open-access papers, as found by Europe PMC text mining. Sharing a sentence is not in itself a finding about the gene and the disease. The quoted sentences say what the papers report.
cholangiocarcinoma (11 papers, 2021 to 2025). A carcinoma that arises from the intrahepatic biliary tree (intrahepatic cholangiocarcinoma) or from the junction, or adjacent to the junction, of the right and left hepatic ducts (hilar cholangiocarcinoma). "CLK3-mediated phosphorylation of USP13 at Tyr708 promotes cholangiocarcinoma progression by activating c-Myc-induced purine synthesis, providing a new and viable therapeutic target for treating cholangiocarcinoma associated with CLK3 mutations." (PMID 36612196, 2022). "Moreover, a recent study also found that CDC-like kinase 3 (CLK3) or the cholangiocarcinoma-associated CLK3-Q607R mutant can directly phosphorylate USP13 at Tyr708, and promote its binding to c-Myc." (PMID 34177595, 2021). "Thus, CLK3-mediated phosphorylation of USP13 at Tyr708 promotes cholangiocarcinoma progression by activating c-Myc-induced purine synthesis, providing a new and viable therapeutic target for the treatment of cholangiocarcinoma associated with CLK3 mutations." (PMID 34177595, 2021). "For example, CDC-like kinase 3 (CLK3) plays a similar role in cholangiocarcinoma cells, and well-known oncogenic kinases such as phosphoinositide 3-kinase (PI3K)/AKT are linked to metabolic gene expression and enzyme activity." (PMID 39762761, 2025). "CLK3 activates the c‐Myc‐mediated transcription of purine metabolic genes by phosphorylating USP13 at Y708 in cholangiocarcinoma." (PMID 35092699, 2022). "Furthermore, CLK3-induced phosphorylation of the Tyr708 residue in USP13 promotes cholangiocarcinoma progression by activating c-Myc-mediated purine synthesis." (PMID 34177595, 2021). "Furthermore, through large-scale small-molecule drug screening, tacrine hydrochloride was found to target CLK3 to treat cholangiocarcinoma, reducing the cholangiocarcinoma tumor formation rate by 85% and reducing the nucleotide level." (PMID 33952722, 2021). "CDC-like kinase 3 (CLK3) is a dual-specificity kinase that functions on substrates containing serine/threonine and tyrosine and is significantly upregulated in cholangiocarcinoma (CCA) and affecting the prognosis of patients through inhibiting purine metabolism." (PMID 35401882, 2022). "In research on nucleotide anabolism in cholangiocarcinoma, CDC like kinase 3 (CLK3) was found to activate the rate-limiting enzyme in de novo purine anabolism, ATIC, by regulating the USP13/Fbxl14/c-Myc signaling axis, thereby promoting the molecular progression of cholangiocarcinoma." (PMID 33952722, 2021).
hepatocellular carcinoma (4 papers, 2022 to 2023). A malignant tumor that arises from hepatocytes. "GTF2H5, BICD1, and CLK3 have been reported to be oncogenes in ovarian cancer and hepatocellular carcinoma and are strongly associated with prognosis." (PMID 36212157, 2022).
colorectal cancer (3 papers, 2023 to 2026). A primary or metastatic malignant neoplasm that affects the colon or rectum. "Previous colorectal cancer studies conform with our findings, and it has been demonstrated that MYC regulates tumor proliferation through various mechanisms, including CLK3 and the Wnt/β-catenin pathway." (PMID 41201451, 2026).
glioma (3 papers, 2022 to 2024). A benign or malignant brain and spinal cord tumor that arises from glial cells (astrocytes, oligodendrocytes, ependymal cells). "In gliomas, the expression of DYRK3 and CLK3 correlated with worse survival, while DYRK1A, DYRK2 and CLK1 were associated with better disease outcomes." (PMID 38398225, 2024). "The phosphorylation of USP13 at Tyrosine 708 by CLK3 is required for USP13′s binding to c-Myc, which prevents its Fbxl14-mediated ubiquitination of c-Myc in glioma stem cells." (PMID 36612196, 2022). "S5B), analysis of the GlioVis Chinese Glioma Genome Atlas (CGGA) dataset shows a significant association of higher expression of CLK2, but not CLK1, CLK3, or CLK4, with poor OS, and CLK2 mRNA expression significantly increases with grade in multiple brain cancers, including GBM." (PMID 35731869, 2022).
breast carcinoma (2 papers, 2018 to 2025). "Among the four CLK family members, CLK3 exhibits high mRNA expression level across 52 breast cancer cell lines and its expression is also the highest in MDA-MB-231 cell line." (PMID 40731028, 2025). "We also observed that the splice factor kinase CLK3, but not CLK2 and CLK4, was also induced in hypoxic DU145 prostate, HT29 colon and MCF7 breast cancer cell lines." (PMID 29606096, 2018).
colon cancer (2 papers, 2022 to 2025). "Our findings indicated that DEDD2, GTF2H5, SNRPA1, BICD1, CELF1, and CLK3 were prognostic risk factors for colon cancer, while ADAD1, CMTR1, HNRNPUL1, FTSJ3, WDR43, THUMPD3, SNRPF were prognostic protective factors." (PMID 36212157, 2022).
cervical cancer (1 paper, 2019). A primary or metastatic malignant neoplasm involving the cervix. "qRT-PCR results showed that the half-life of circCLK3 exceeded 24 h in SiHa and HeLa cells, while that of CLK3 mRNA was <6 h, and that compared with linear mRNA CLK3, circCLK3 was more capable of resistance to digestion of RNase R, indicating that circCLK3 is highly stable in cervical cancer cells." (PMID 31831728, 2019).
malaria (1 paper, 2020). Malaria is a serious and sometimes fatal disease caused by a parasite that commonly infects a certain type of mosquito which feeds on humans. "It has been demonstrated that CLK3 inhibition can kill multiple species of malaria parasites at the blood stage and at the liver-stage and block transmission of the parasite to mosquitoes." (PMID 33066143, 2020). "Finally, it has been reported that inhibition of CLK3 in Plasmodium falciparum (PfCLK3) represents a promising approach for the treatment of malaria via preventing the splicing of essential parasite genes." (PMID 33066143, 2020).
viral infection (1 paper, 2024). "Notably, the viral infection also led to marked changes in the expression of select SR kinases, though the specific kinase affected varied between the viruses and cell lines: influenza PR8 infection of A549 cells reducing CLK1 levels while HCoV-229E infection of Huh7 cells decreased CLK3 abundance." (PMID 39861843, 2024).
tumor (7 papers, 2018 to 2026). "Previous research suggests that simultaneous inhibition of both CLK2 and CLK3 results in a more pronounced anti‐tumor effect, highlighting their significance as potential therapeutic targets." (PMID 38723164, 2024). "Despite the availability of reasonably accurate m1A detection methodologies for monitoring its role in tumor development, the precise m1A modification sites remain elusive, particularly in cases such as CRC where m1A has been shown to regulate the MFAP2/CLK3 axis." (PMID 38291517, 2024).
cancer (5 papers, 2018 to 2025). A tumor composed of atypical neoplastic, often pleomorphic cells that invade other tissues. "The elevated expression of these splicing regulators, such as Clk1 and Clk3, helps cells adapt through the AS of key cancer-associated genes." (PMID 37658940, 2023). "Typically, CLK3 is expressed in male testes and sperm, by contrast, as a potential cancer treatment target, the expression level of CLK1 in testicular tissue is significantly lower than other isoforms." (PMID 40599151, 2025). "The most potent analogues were further tested against three highly homologous kinases, Clk2, Clk3, and Haspin, which are equally involved in several types of cancers." (PMID 38893153, 2024). "CLK3 is best known for its expression in normal testis; however we suggest that along with CLK1, CLK3 might contribute to adaptation to hypoxia in cancer cells." (PMID 29606096, 2018).
CLK3 also shares sentences with these, for which no sentence is quoted: Alzheimer disease (1 paper); brain cancer (1); gastric cancer (1); liver cancer (1); ovarian carcinoma (1); pancreatic cancer (1); prostate adenocarcinoma (1).